ADIPOR2 (adiponectin receptor 2)
Diseases named in the same sentence as ADIPOR2 in open-access papers (continued):
Sharing a sentence is not in itself a finding about the gene and the disease.
ADIPOR2 also shares sentences with these, for which no sentence is quoted: diabetic nephropathy (3 papers); Nephropathy (2); type 2 diabetic nephropathy (2); acute myeloid leukemia (1); adrenocortical carcinoma (1); allergic disease (1); Barrett esophagus (1); bladder urothelial carcinoma (1); bone metabolic disorders (1); brain injury (1); chronic myeloid leukemia (1); chronic obstructive pulmonary disease (1); chronic renal failure (1); colorectal adenocarcinoma (1); coronary atherosclerosis (1); dementia (1); diffuse large B-cell lymphoma (1); endometrial adenocarcinoma (1); gestational diabetes (1); gout (1); Hypocholesterolemia (1); Hypoxemia (1); infectious disease (1); Infertility (1); kidney injuries (1); liver inflammation (1); lymph node metastasis (1); lymphoid neoplasm (1); mesothelioma (1); ovarian cancer (1).
A further 10 diseases each share a sentence with ADIPOR2 in 1 paper.